KRABD2 (KRAB domain containing 2)
Synonyms: KRBA2
Tractability: No criterion of Open Targets' tractability assessment is met for any kind of drug.
Gene: Protein-coding gene on chromosome 17 (8,356,902 to 8,376,738, reverse strand). Ensembl gene ENSG00000184619.
Subcellular location (Human Protein Atlas): Nucleoplasm
Gene Ontology:
Molecular function: protein binding; nucleic acid binding
Biological process: DNA integration; regulation of DNA-templated transcription
Genetic constraint (gnomAD): Loss-of-function variants: 1 observed, 2.27 expected, observed/expected ratio (o/e) 0.44, 90% interval 0.15 to 1.68. That is too few expected variants to judge how well the gene tolerates losing a copy. Missense variants: 451 observed, 530.89 expected, observed/expected ratio (o/e) 0.85, 90% interval 0.79 to 0.92. Synonymous variants: 135 observed, 181.55 expected, observed/expected ratio (o/e) 0.74, 90% interval 0.65 to 0.86.
Homologues: Orthologues: chimpanzee KRBA2 (99% identical), macaque KRBA2 (95% identical), dog KRBA2 (87% identical).
Diseases named in the same sentence as KRABD2 in open-access papers:
KRABD2 is named in the same sentence as 1 disease in open-access papers, as found by Europe PMC text mining. Sharing a sentence is not in itself a finding about the gene and the disease.
KRABD2 shares sentences with these, for which no sentence is quoted: melanoma (1 paper).